GDF15 (growth differentiation factor 15)
Diseases named in the same sentence as GDF15 in open-access papers (continued):
Sharing a sentence is not in itself a finding about the gene and the disease.
glaucoma (continued). "This platform detected growth differentiation factor-15 (GDF15), a biomarker for glaucoma and aging, with an exceptionally low LoD of 5–6 pg/mL." (PMID 41294748, 2025). "Overall, although there is an increase in the levels of both AH and serum GDF15 levels in severe POAG patients compared to mild POAG patients, there was no statistical difference between these two groups in the small cohort of glaucoma patients examined." (PMID 35160195, 2022). "By measuring plasma GDF-15 in HTG and NTG patients, and controls, we aimed to gather indications on the role of mitochondrial dysfunction in glaucoma." (PMID 34048486, 2021). "The reason for the noted discrepancy between levels of GDF15 in serum and plasma derived from glaucoma patients is not clear." (PMID 35160195, 2022). "We want to recognize the limitations of this study in regards to a lack of a definitive correlation between the levels of AH GDF15 and the disease severity of glaucoma." (PMID 35160195, 2022). "In this study, we evaluated the levels of GDF15 in aqueous humor (AH) and serum samples derived from primary open-angle glaucoma (POAG) and age- and gender-matched non-glaucoma (cataract) patients to assess the plausible association between GDF15 and POAG." (PMID 35160195, 2022). "Interestingly, in the AH of CMV-HAU, GDF-15, which belongs to the TGF-β superfamily proteins, it showed a 40-fold increase compared to the non-glaucoma controls." (PMID 35566463, 2022). "Moreover, GDF15 was found to be elevated in the RGC and AH in different glaucoma experimental models, wherein a good correlation has been documented between RGC loss and increased expression and protein levels of GDF15." (PMID 35160195, 2022). "In fact, in this past study, ∼88% of patients without glaucoma had AH GDF15 levels that were below the limit of detection of commercially available ELISA." (PMID 32983624, 2020). "Although we did not recruit healthy patients without glaucoma in this study, these AH GDF15 levels were significantly elevated compared to a historical control group of patients without glaucoma, which we published previously (P < 0.001)." (PMID 32983624, 2020). "Indeed, an approximately 60-fold increase in GDF-15 was observed in glaucomatous AH, suggesting that measuring GDF-15 to demonstrate a role for mitochondrial dysfunction in a glaucoma patient may still be valid option, but has to be done in local tissue." (PMID 34048486, 2021). "Currently, it is not known whether glaucoma eye drops have an effect on blood GDF-15 levels." (PMID 34048486, 2021). "The second reason is that we do not know the implications of prior eye surgeries for GDF15 levels, since some POAG patients had previously undergone cataract removal and glaucoma procedures, and corneal, or retinal intraocular surgery." (PMID 35160195, 2022). "Plasma GDF-15 concentrations were measured with ELISA in 200 OAG patients and 61 age-matched controls (cataract without glaucoma)." (PMID 34048486, 2021).
MELAS (11 papers, 2016 to 2025). "Our results confirmed the association between FGF21/GDF-15 and mitochondrial diseases due to translation defects (MELAS and MERRF) with skeletal muscle involvement." (PMID 32851462, 2020). "Highest levels of GDF-15 were present in the serum of patients with thymidine kinase 2 (TK2) defects, MELAS, defects in MT-TL1 encoding mitochondrial tRNA leucine, and patients with Pearson syndrome and KSS." (PMID 36361969, 2022). "All together, these two phenotypic subgroups, i.e. patients with tRNA point mutations (MELAS and MERRF), confirm that mtDNA translation defects are hallmarked by FGF21 and GDF-15." (PMID 32851462, 2020). "It seems that GDF15 levels in serum are higher in mitochondrial disease patients with multisystem involvement, like MELAS or Pearson/KSS patients." (PMID 32397676, 2020). "Amongst patients with the highest levels of GDF-15 were children with mutations in TK2, patients with MELAS and the common mutations in the MT-TL1 gene and patients with deletions in mtDNA including one patient with Pearson Syndrome and two patients with KSS." (PMID 26867126, 2016). "In a cohort of 48 patients diagnosed with mitochondrial encephalomyopathy, lactic acidosis, and stroke-like episodes (MELAS), Leigh syndrome or Kearns-Sayre syndrome (KSS), serum GDF-15 had an impressive diagnostic sensitivity and specificity nearing 100% and AUC of 0.997." (PMID 36361969, 2022). "In this study, mean GDF15 levels were ranked in the following order: Leigh syndrome (LS); mitochondrial encephalopathy, lactic acidosis, and stroke-like episodes (MELAS); Kearns–Sayre syndrome (KSS); overlapping MELAS/LS; and mitochondrial encephalopathy and lactic acidosis (MELA)." (PMID 32397676, 2020). "We evaluated the correlations between FGF21 and GDF15 and various phenotypes/genotypes, including syndromic/non-syndromic PMDs, different mitochondrial syndromes (MELAS, Leigh syndrome, etc.), nDNA/mtDNA pathogenic variants, gene functions, and different organ/system involvement." (PMID 35498801, 2022). "GDF-15 levels were assessed in six patients (two CPEO, one limb myopathy, one limb myopathy+, one multisystem, one MELAS) and elevated in all (median 1965 pg/mL, IQR 1591–2894 pg/mL)." (PMID 38434220, 2024). "Some studies found that GDF15 or FGF21 levels were higher in some specific phenotypes of PMDs, for example, in patients with TK2 defects, MELAS, or muscle manifestations." (PMID 35498801, 2022). "In MD patients, serum GDF15 concentrations were higher in patients with MELA, KSS, MELAS, and LS than in healthy controls." (PMID 32965044, 2021). "In this study, FGF21 and GDF15 were predominantly elevated in patients with a primary muscular phenotype (CPEO, CPEO-plus), while not significantly altered in mitochondriopathies with concomitant CNS manifestation (MELAS)." (PMID 39891741, 2025). "Previously, the fibroblast growth factor 21 (FGF21) and the growth differentiation factor 15 (GDF15) have been used as biomarkers for mitochondrial translation and mtDNA maintenance disorders, or mitochondrial encephalomyopathy, lactic acidosis and stroke-like episodes (MELAS), respectively." (PMID 39288270, 2024). "However, there was a tendency for higher CHIT1 concentrations in patients with central nervous system involvement (MELAS syndrome), while FGF21 and GDF15 were not relevantly altered in these patients." (PMID 39891741, 2025).
psoriasis (11 papers, 2021 to 2026). An autoimmune condition characterized by red, well-delineated plaques with silvery scales that are usually on the extensor surfaces and scalp. "The findings revealed that serum levels of GDF-15 were higher in patients with more severe forms of psoriasis than those with milder cases." (PMID 40343299, 2025). "The research investigated how serum levels of GDF-15 correlated with its gene expression in patients with psoriasis." (PMID 40343299, 2025). "The authors highlighted that serum levels and gene expression of GDF-15 were higher in psoriasis patients compared to the control group and positively correlated with disease severity." (PMID 38399624, 2024). "They demonstrated a significant association between serum GDF-15 levels and psoriasis, as well as between GDF-15 gene expression and psoriasis." (PMID 38668313, 2024). "On the other hand, we found that GDF-15 was increased in patients with psoriasis with prior CVD, which is consistent with results from previous studies of patients without psoriasis." (PMID 34728734, 2021). "Likewise, the gene expression of GDF-15 was more significant in individuals with more severe psoriasis." (PMID 40343299, 2025). "Furthermore, a recent study shows that GDF-15 can be used as a marker to detect subclinical cardiovascular disease in patients with moderate to severe psoriasis." (PMID 38399624, 2024). "It should be mentioned that some studies have found a negative association between GDF-15 and vascular inflammation in the ascending and entire aorta in patients with psoriasis." (PMID 38396781, 2024). "GDF-15 was significantly higher in all three patient groups (mild, moderate, severe psoriasis)." (PMID 38668313, 2024). "Upregulation of GDF15 at both 6 h and 18 h in psoriasis plaques post 311 nm UVB may therefore represent activation of a signalling pathway that has the potential to contribute to psoriatic plaque resolution and anti-atherogenic activity." (PMID 33812333, 2021). "Additionally, GDF15 has been reported to inhibit the activation of the small GTPase Rap1 and to block activation of β2-integrin affinity and clustering, thereby preventing neutrophil adhesion and migration in a psoriasis models and a cardiac infarction model." (PMID 40673270, 2025). "A recent study examined the relationship between growth differentiation factor-15 (GDF-15), a transforming growth factor-β (TGF-β) superfamily member with recognized immunomodulatory roles and the severity of psoriasis." (PMID 40343299, 2025). "Among patients with psoriasis and without CVD, GDF-15 levels were negatively associated with vascular inflammation and positively associated with carotid artery intima-media thickness (CIMT) and coronary calcium score (CCS)." (PMID 38396781, 2024). "Among patients with psoriasis without CVD and statin treatment, GDF-15 levels were negatively associated with vascular inflammation in the ascending aorta and entire aorta, and positively associated with CIMT and CCS." (PMID 34728734, 2021). "In conclusion, GDF-15 and NLR may serve as biomarkers of subclinical CVD in patients with a history of moderate-to-severe psoriasis." (PMID 34728734, 2021). "To further validate findings from our transcriptional analysis, we performed immunohistochemical analysis focusing on selected apoptotic and cell cycle regulatory proteins (FOSL1, GDF15, JUNB and CDKN1A) in lesional psoriasis skin (control) and 24 h after 311 nm or 290 nm irradiation." (PMID 33812333, 2021).
anorexia nervosa (10 papers, 2012 to 2026). A disorder most often seen in adolescent females characterized by a refusal to maintain a minimally normal body weight, an intense fear of gaining weight, a disturbance in body image, and, in postmenarcheal females, the development of amenorrhea. "GDF15 predicted the BMI of patients with anorexia nervosa and individuals from the general population, again being elevated at lower BMI (linear regression beta −0.254, p‐value 0.005)." (PMID 40708105, 2026). "Here we analyze GDF15 in anorexia nervosa (AN), a psychiatric disorder characterized by low weight and persistent restriction of food intake." (PMID 40562759, 2025). "Plasma GDF15 correlated to body weight and BMI in the control group and in patients with anorexia nervosa." (PMID 36545337, 2022). "The present study demonstrates that patients with anorexia nervosa have higher plasma GDF15 than matched controls." (PMID 36545337, 2022). "Finally, GDF15 was assessed both during short-term (36 hours) fasting and in patients with anorexia nervosa." (PMID 36545337, 2022). "In addition, both low albumin and elevated alanine aminotransferase are markers for evaluating liver function, indicating that hepatic “stress” mediates an increase in plasma GDF15 in patients with anorexia nervosa." (PMID 36545337, 2022). "This would point to antagonizing GDF15 as a therapeutic target for treatment of anorexia nervosa." (PMID 36545337, 2022). "However, plasma GDF15 was 1.4-fold higher in patients with anorexia nervosa than in age-matched healthy subjects." (PMID 36545337, 2022). "GDF15 correlated with low albumin and high levels of alanine aminotransferase in the anorectic group but not in the control group, which supports that GDF15 in patients with anorexia nervosa may be liver-derived." (PMID 36545337, 2022). "Fasting for 36 hours did not affect circulating GDF15, whereas resting patients with anorexia nervosa displayed elevated plasma concentrations (1.4-fold, P<0.05) compared to controls." (PMID 36545337, 2022). "Of note it could be speculated the elevated GDF15 concentration observed in patients with anorexia nervosa could be a part of the pathology and not secondary to the energy deprivation." (PMID 36545337, 2022).
end-stage renal disease (10 papers, 2016 to 2025). "Elevated plasma levels of GDF15 have been linked to end-stage renal failure." (PMID 33003626, 2020).
injury (10 papers, 2019 to 2024). Damage inflicted on the body as the direct or indirect result of an external force, with or without disruption of structural continuity. "On the other hand, GDF15 expression dramatically increases following liver injury, while its overexpression ameliorates ischemia-reperfusion injury and leads to improved functional recovery following a traumatic spinal cord injury." (PMID 39307303, 2024). "In addition, GDF15 has been found to affect the recruitment of neutrophils in the post-capillary venules of the cremaster muscle in a ventilator-induced lung injury model." (PMID 37093513, 2024). "In support of this hypothesis, experimental data have demonstrated that GDF-15 was locally overexpressed in rodent models of brain injury." (PMID 31624933, 2019). "Similarly, GDF15, another member of the GDF family, can upregulate SIRT1 expression in lipopolysaccharide-induced acute lung injury." (PMID 34262905, 2021). "However, external administration of GDF-15 did not produce harmful effects; instead, it induced a pro-regenerative response that enhanced proliferation following cartilage trauma and exhibited protective properties for cartilage and cells." (PMID 39329976, 2024).
lung disease (10 papers, 2014 to 2024). "As a secreted protein, GDF15 can be used as not only a predictor of all-cause mortality but also a biomarker for the diagnosis, progression assessment, and prognosis of various lung diseases." (PMID 37093513, 2024). "In the context of lung disease, GDF15 levels have been associated with an increased frequency of exacerbations, subclinical cardiovascular disease, declining lung function, and poor outcomes in chronic obstructive pulmonary disease." (PMID 31432710, 2019). "As a molecule closely associated with stress and the ageing process, GDF15 is linked to the pathogenesis of several lung diseases, particularly chronic lung diseases; however, several inconsistencies remain with the molecular mechanism underlying GDF15 function at the cellular level." (PMID 37093513, 2024). "A recent study determined that GDF15 levels correlate with age and with the extent of interstitial lung abnormalities and mortality in lung disease." (PMID 35993367, 2022). "The GDF-15 level provides independent prognostic information about cardiovascular disease and lung disease." (PMID 35095877, 2021). "GDF15 contributes to the pathophysiology of many lung diseases in which senescence plays a role as well." (PMID 33344478, 2020). "The role of GDF15 in neonatal and pediatric lung disease needs further research toward elucidating its role in alveolarization and pathogenesis of chronic lung disease related to prematurity and other pediatric conditions." (PMID 33344478, 2020). "This review focuses on the role of GDF15 in different lung diseases across the lifespan and its role in cellular senescence." (PMID 33344478, 2020). "We attempted to review the role of GDF15 in lung diseases in which cellular senescence plays a key role." (PMID 33344478, 2020). "What are the transcription factors upstream modulating GDF15 expression in the spectrum of lung diseases?" (PMID 33344478, 2020). "The interest in GDF15 as a senescence associated protein is growing, and so is the role of senescence in lung diseases, the intersection between the two reveals many areas of research which will elucidate the role of GDF15." (PMID 33344478, 2020). "Our study further connects telomere dysfunction with pulmonary disease, as we identified GDF15 while studying an animal model of AEC2-specific telomere dysfunction." (PMID 31432710, 2019). "GDF15 is also involved in the aetiology of other lung diseases." (PMID 37093513, 2024). "Since CS exposure increases GDF15 expression at baseline, this could predispose patients with COPD to respiratory viruses and lead to acute exacerbation of their lung disease." (PMID 33344478, 2020). "Based on the current state of literature about GDF15, its role in cellular senescence and in lung diseases across the lifespan, the following gaps on the role of GDF15 in lung diseases are identified: Do recruited inflammatory cells increase GDF15 levels in the lung?" (PMID 33344478, 2020). "Is GDF15 expression an adaptive, protective or harmful response in a specific lung disease?" (PMID 33344478, 2020). "List of GDF15 functions and mechanisms on different lung diseases." (PMID 33344478, 2020). "GDF-15 was shown to be involved in promoting anti-inflammatory pathways in several pathologic conditions including inflammation, cancer, cardiovascular disease, and pulmonary disease." (PMID 29682097, 2018).
non-small cell lung carcinoma (10 papers, 2013 to 2026). A group of at least three distinct histological types of lung cancer, including non-small cell squamous cell carcinoma, adenocarcinoma, and large cell carcinoma. "In patients with stage I and II non-small cell lung cancer, multivariate Cox regression survival analysis showed that high GDF-15 in serum was an independent risk factor for reduced overall survival (HR = 3.37, 95% CI: 1.09–10.42, p = 0.035)." (PMID 32508832, 2020). "This study aimed to investigate GDF15 levels as a predictive marker in advanced non-small cell lung cancer (NSCLC) treated with PD-1/PD-L1 inhibitors and analyze their association with immune cell populations." (PMID 36472770, 2023). "In locally advanced non-small cell lung cancer (NSCLC) treated with chemoradiotherapy, elevated GDF15 levels correlate with worse recurrence-free survival (RFS) and OS, highlighting its prognostic relevance." (PMID 40868185, 2025).
nonalcoholic steatohepatitis (10 papers, 2018 to 2026). "Mice that express GDF15 expression have reduced nonalcoholic steatohepatitis, an inflammatory condition in the liver." (PMID 40673270, 2025). "A recent study showed that ARRB1 inhibited nonalcoholic steatohepatitis progression by promoting growth differentiation factor 15 maturation." (PMID 34455423, 2021). "For example, in mouse models of non-alcoholic steatohepatitis, downregulated ARRB1 in hepatocytes impairs the transport of GDF15 precursor to the Golgi apparatus for cleavage and maturation, thereby promoting intracellular lipid accumulation." (PMID 40677718, 2025).